KLHL41 (kelch like family member 41)
Description:
Involved in skeletal muscle development and differentiation. Regulates proliferation and differentiation of myoblasts and plays a role in myofibril assembly by promoting lateral fusion of adjacent thin fibrils into mature, wide myofibrils. Required for pseudopod elongation in transformed cells.
Synonyms: KBTBD10; KRP1; SARCOSIN
Tractability: Antibody: its Gene Ontology location is reachable by antibodies, with high confidence. PROTAC: UniProt records ubiquitination sites on it; ubiquitination databases record sites on it.
Gene: Protein-coding gene on chromosome 2 (169,509,687 to 169,526,262, forward strand). Ensembl gene ENSG00000239474.
Subcellular location: Cytoplasm; Cytoplasm, cytoskeleton; Cell projection, pseudopodium; Cell projection, ruffle; Cytoplasm, myofibril, sarcomere, M line; Sarcoplasmic reticulum membrane; Endoplasmic reticulum membrane
Subcellular location (Human Protein Atlas): Cytosol; Nucleoplasm; Plasma membrane
Pathways (Reactome):
Immune System: Antigen processing: Ubiquitination & Proteasome degradation
Metabolism of proteins: Neddylation
Gene Ontology:
Molecular function: protein binding; ubiquitin-like ligase-substrate adaptor activity
Biological process: protein ubiquitination; myofibril assembly; proteasome-mediated ubiquitin-dependent protein catabolic process; regulation of myoblast differentiation; regulation of myoblast proliferation; regulation of skeletal muscle cell differentiation; skeletal muscle cell differentiation; striated muscle contraction
Cellular component: Cul3-RING ubiquitin ligase complex; cytoplasm; cytosol; endoplasmic reticulum membrane; sarcoplasmic reticulum membrane; cytoskeleton; M band; pseudopodium; ruffle
Genetic constraint (gnomAD): Loss-of-function variants: 23 observed, 39.27 expected, observed/expected ratio (o/e) 0.59, 90% interval 0.42 to 0.83. The synonymous counts are far from expectation, so gnomAD's model fits this gene poorly and the ratio says little. Missense variants: 583 observed, 667.4 expected, observed/expected ratio (o/e) 0.87, 90% interval 0.81 to 0.94. Synonymous variants: 190 observed, 241.66 expected, observed/expected ratio (o/e) 0.79, 90% interval 0.7 to 0.89.
Gene-disease validity (ClinGen):
ClinGen rates the evidence that KLHL41 causes each of these diseases.
nemaline myopathy 9 (autosomal recessive): Moderate. Any nemaline myopathy in which the cause of the disease is a mutation in the KLHL41 gene.
Homologues: Orthologues: chimpanzee KLHL41 (100% identical), macaque KLHL41 (99% identical), dog KLHL41 (98% identical), pig KLHL41 (98% identical), rabbit KLHL41 (97% identical), mouse Klhl41 (95% identical), rat Bbs5 (95% identical), guinea pig KLHL41 (93% identical), tropical clawed frog klhl41 (76% identical), zebrafish klhl41b (61% identical), zebrafish klhl41a (60% identical). Paralogues in human: KLHL40 (50% identical), KLHL20 (26% identical), KLHL3 (25% identical), KLHL12 (24% identical), KLHL38 (24% identical), KLHL4 (24% identical), KLHL17 (24% identical), KLHL2 (24% identical), KLHL29 (23% identical), KLHL18 (23% identical), GAN (23% identical), KLHL5 (23% identical), and 42 more.
Diseases named in the same sentence as KLHL41 in open-access papers:
KLHL41 is named in the same sentence as 25 diseases in open-access papers, as found by Europe PMC text mining. Sharing a sentence is not in itself a finding about the gene and the disease. The quoted sentences say what the papers report.
nemaline myopathy (16 papers, 2014 to 2024). Nemaline myopathy (NM) encompasses a large spectrum of myopathies characterized by hypotonia, weakness and depressed or absent deep tendon reflexes, with pathologic evidence of nemaline bodies (rods) on muscle biopsy. "KLHL41 (formerly, KBTBD10), a gene whose recessive coding mutations can cause nemaline myopathy, had much higher expression in SkM (TPM, 3420) than did any other KLHL family gene and much lower expression in other tissues." (PMID 33182325, 2020). "Both overexpression and loss of KLHL41 have been shown to cause nemaline myopathy-like phenotypes, implying that its regulation is critical to sarcomeric structure." (PMID 31992366, 2020). "We also studied the recently-discovered proteins associated with the development of nemaline myopathy, KLHL41 and NRAP." (PMID 31992366, 2020). "Molecular analysis in zebrafish shows that knockdown of Klhl41 causes nemaline myopathy-like abnormalities, characterized by aberrant myofibril formation." (PMID 33114658, 2020). "Mutations in Kelch-like protein 41 (KLHL41) cause nemaline myopathy, a fatal muscle disorder associated with sarcomere disarray." (PMID 28826497, 2017). "Evidence for the functional significance of BACK domains comes from recent studies where missense mutations in this domain in KLHL40 and KLHL41 are pathogenic in human patients affected with nemaline myopathy." (PMID 24959344, 2014). "KLHL41 also interacts with nebulin, a known causative gene of nemaline myopathy, by protein-protein interactions and is co-localized with actin at the tips of pseudopodia in fibroblasts." (PMID 24959344, 2014). "More recently, KLHL41 (kelch like family member 40) mutations, encoding for nebulin-interacting homonymous protein, which is important in myofibril maturation, are also associated with mainly severe early onset forms of nemaline myopathy." (PMID 32456280, 2020). "KLHL9, KBTBD13, KLHL40, and KLHL41 have been implicated in distal and nemaline myopathy." (PMID 31985165, 2020). "In humans, mutations in Klhl41 are also associated with nemaline myopathy development." (PMID 33114658, 2020). "KLHL41 interacts with nebulin and co-localizes with actin, mutations of which cause approximately 65% to 70% of all known mutations in patients affected with nemaline myopathy." (PMID 24959344, 2014). "Similarly, mutations in Kelch repeats of both KLHL40 or KLHL41 also result in nemaline myopathy." (PMID 24959344, 2014). "NRAP is involved in myoblast fusion and myofibril assembly, and its accumulation has been detected in mouse and zebrafish models of KLHL41-related nemaline myopathy." (PMID 36703211, 2023). "KLHL41 degrades nebulin-related anchoring protein, and this degradation is dysregulated in nemaline myopathy." (PMID 32938372, 2020). "Mouse models of KLHL40 and KLHL41 nemaline myopathy showed early lethality (within days to weeks from birth)." (PMID 31228046, 2019). "Loss of KLHL41 or inhibition of its poly-ubiquitination leads to NEB aggregation, sarcomere disarray and nemaline myopathy." (PMID 28826497, 2017). "Unlike KLHL9 and KBTBD13 mutations that cause a dominant form of the disease, mutations in KLHL41, like KLHL40, result in an autosomal recessive form of nemaline myopathy." (PMID 24959344, 2014). "An amino acid alignment of only the Kelch repeat regions shows that proteins involved in similar disease processes are clustered together (for example, KLHL40, KLHL41, and KBTBD13, all of which cause nemaline myopathy)." (PMID 24959344, 2014). "Interestingly, mutations in KLHL41 and NEB are associated with subtypes of nemaline myopathy, further connecting these proteins to myodegeneration in SBMA." (PMID 38973610, 2024). "Importantly, we did not observe increased expression of these DNA damage–related genes in mouse models of other muscle disorders, including Duchenne muscular dystrophy (Dmd ΔEx51 mice) and nemaline myopathy (Klhl41-KO mice)." (PMID 37395273, 2023).
nemaline myopathy (continued). "Several genes among the Kelch-like family members are involved in nemaline myopathy; Kelch-like protein 40 (KLHL40) decreases thin filament protein stability, KBTBD13 disorganises the Z-disc, and Kelch-like protein 41 (KLHL41) impacts on nebulin degradation." (PMID 32938372, 2020). "Kelch-like family member 41, KLHL41, was selected for its role in nebulin stabilization as well as possible ubiquitination processes in nemaline myopathy." (PMID 31992366, 2020). "As most of the previously known NM proteins are components of sarcomeric thin filaments, the unique localization of KLHL41, as well as non-sarcomeric localization of KLHL40 in association with the triads, suggests the involvement of new pathophysiological mechanisms for nemaline myopathy." (PMID 24959344, 2014).
cardiomyopathy (2 papers, 2017 to 2024). A disease of the heart muscle or myocardium proper. "In contrast to LMOD3, LMOD2, another member of the LMOD family involved in thin filament shortening and cardiomyopathy, was also up-regulated in Klhl41 KO mice both at protein and mRNA levels." (PMID 28826497, 2017).
congenital myopathy (2 papers, 2016 to 2023). "In particular, KLHL40 and KLHL41, that functions as substrate-specific adaptors for E3 ubiquitin ligase CUL3, contribute to severe forms of congenital myopathy with neonatal lethality with extensive sarcomeric disarray and contractures." (PMID 37432316, 2023).
melanoma (2 papers, 2018 to 2022). A malignant, usually aggressive tumor composed of atypical, neoplastic melanocytes. "While expression of one of the signature genes (KLHL41) is high in metastatic melanomas (potentially promoting tumor progression), expression of the other seven genes is high in low-risk melanomas (potentially reflecting stromal tumor suppression)." (PMID 31360859, 2018). "Finally, the risk gene KLHL41 promotes elongation of pseudopods in transformed cells and hence might stimulate melanoma cell invasion." (PMID 31360859, 2018). "Intriguingly, the prognostic power of most signature genes (except of KLHL41) was increased by more than 10-fold in FFPE melanomas when compared with their FF counterparts." (PMID 31360859, 2018). "While three of the signature genes (KLHL41, KRT9, GBP4) have not been reported so far to be expressed in melanoma, there is functional evidence for all signature genes suggesting that they might be involved in immune responses, inflammation, or tumor progression." (PMID 31360859, 2018).
steatosis (1 paper, 2025). Increased lipid within the cytoplasm of cells. "Specifically, H4C1, OIT3, ANPEP, CCDC25 and KLHL41 were identified as potential biomarkers for steatosis, GP1BA as a candidate marker for MASH and C7, IGHD and GNB1 as potential biomarkers for fibrosis severity." (PMID 41301514, 2025).
myopathy (3 papers, 2017 to 2023). A disease of the muscle in which the muscle fibers do not function properly. "We have previously shown that reduced ubiquitylation and upregulated protein level of an early sarcomeric protein, NRAP, in KLHL41 deficient skeletal muscle contributes to myopathy by abnormal sequestration of the late sarcomeric proteins and preventing their localization to mature sarcomeres." (PMID 37432316, 2023). "Interestingly, when this protein is removed in KLHL41-deficient muscle, the myopathy phenotypes are reversed." (PMID 31992366, 2020).
neuromuscular disease (3 papers, 2015 to 2024). "Four novel genes related to neuromuscular diseases were found, consisting of GPR126, KLHL40, KLHL41, and SPEG genes." (PMID 37989827, 2024). "The study also led to the identification of novel neuromuscular disease genes (KLHL40, KLHL41, and LMOD3) involved in sarcomere assembly and muscle dysfunction." (PMID 26933539, 2015). "The study has also resulted in the identification of four novel neuromuscular disease genes, and has led to the identification of a novel mechanism of sarcomere assembly and muscle dysfunction involving KLHL40, KLHL41 and LMOD3." (PMID 26578207, 2015). "Mutations were found in eight previously known neuromuscular disease genes (CHRND, CHNRG, ECEL1, GBE1, MTM1, MYH3, NEB and RYR1) and four novel neuromuscular disease genes (GPR126, KLHL40, KLHL41 and SPEG)." (PMID 26933539, 2015). "Within this cohort, mutations were found in eight previously known neuromuscular disease genes (CHRND, CHNRG, ECEL1, GBE1, MTM1, MYH3, NEB and RYR1) and four novel neuromuscular disease genes were identified and have been published as separate reports (GPR126, KLHL40, KLHL41 and SPEG)." (PMID 26578207, 2015).
tumor (2 papers, 2018 to 2022). "Immunohistochemistry of primary tumor tissue was performed for eight proteins: COL6A6, DCD, GBP4, KLHL41, KRT9, PIP, SCGB1D2, SCGB2A2." (PMID 34757537, 2022).
cancer (1 paper, 2019). A tumor composed of atypical neoplastic, often pleomorphic cells that invade other tissues. "MYO1F, SASH3 and KLHL41 are the candidate pathogenic genes that shared with multi-cancers in this paper." (PMID 31888692, 2019).
KLHL41 also shares sentences with these, for which no sentence is quoted: congenital nemaline myopathies (2 papers); cryptococcosis (2); muscle disorder (2); adenocarcinoma (1); breast carcinoma (1); candidiasis (1); colon cancer (1); distal myopathy (1); Duchenne muscular dystrophy (1); embryonal carcinoma (1); epidermolysis bullosa simplex (1); gastric cancer (1); infection (1); metastatic melanoma (1); nasopharyngeal carcinoma (1); prostate carcinoma (1).